MTOR (mechanistic target of rapamycin kinase)
Diseases named in the same sentence as MTOR in open-access papers (continued):
Sharing a sentence is not in itself a finding about the gene and the disease.
tumor (continued). "Also, the marked inhibition of tumor growth obtained by two different approaches (local overexpression by the tumor and by systemic administration) confirms that SEMA3F is a potent mTOR inhibitor in vivo." (PMID 26156437, 2015). "Paradoxically, mTOR but not MEK inhibition resulted in durable tumor control following cessation of therapy in immunogenic MOC1 but not poorly immunogenic MOC2 tumors." (PMID 26506415, 2015). "However, IGF-I and other growth/survival factors produced in the local tumor microenvironment activate the PI3K/Akt pathway, exert an anti-apoptotic effect, and are also known to inhibit autophagy through mTOR." (PMID 25741318, 2015). "Taken together, our results demonstrated that PTEN is a potent tumor suppressor in human SGTs, and targeting PI3K/mTOR pathway may be effective in the targeted therapy for human SGT patients with loss of PTEN expression." (PMID 25909167, 2015). "Therefore, in vivo SEMA3F is likely to have an impact on tumor growth via both the suppression of VEGF secretion and direct inhibition of Akt-mTOR signaling." (PMID 26156437, 2015). "We also showed that FVII-PAR2 signaling is a contributor to tumor migration in HCC, which may through both mTOR-dependent and mTOR-independent pathways." (PMID 27551480, 2015). "The treatment of a panel of PDXs representing multiple triple-negative subtypes with mTOR inhibitors led to significant tumor growth inhibition but no tumor was eradicated, indicating the need for testing combinational therapies in future investigations." (PMID 25849559, 2015). "The PI3K/mTOR and the MAPK pathway are commonly phosphorylated in this tumor type." (PMID 26314846, 2015). "The effects of PI3K/mTOR and MAPK pathway targeting agents on anti-tumor immunity are of interest given the demonstrated activity of immune checkpoint inhibitors in HNSCC and the potential for enhanced patient responses with combining these immune-modulators with targeted therapies." (PMID 26506415, 2015). "Controversy surrounds whether metformin's antitumorigenic benefits stems from its indirect effects via decreasing circulating insulin and glucose levels or its direct effects in tumor cells via AMPK activation and inhibition of the mTOR pathway." (PMID 25417601, 2015). "The tumor exhibited an extremely aggressive clinical behavior during radiotherapy and was non-responsive to mTOR inhibitor, and moreover showed only modest response to a variety of medical interventions and TKIs." (PMID 26654961, 2015). "It is tempting to speculate that the multi-Akt inhibition could represent an effective treatment to block crosstalk between PI3K/Akt/mTOR and Raf/MEK/ERK reducing tumor growth and cells proliferation." (PMID 25788264, 2015). "Considering that the PI3K/PKB/mTOR signaling can be an important machinery for tumor cell survival and anabolic metabolism, the functional impact of SESN2 on the regulation of PTEN/PKB signaling in tumor deserves further studies." (PMID 25792980, 2015). "As expected and in accordance with published results for different tumor entities, the treatment with AZD6244 and NVP-BEZ235 alone resulted in inhibition of the MAPK and PI3K/mTOR signaling cascade, respectively, as confirmed by reduced expression of p-Erk, p-Akt, p-S6 and p-4E-BP1." (PMID 26498922, 2015). "Interestingly, we found that rapamycin inhibited mTOR signaling in addition to simultaneously downregulating the expression of CD44, SOX2 and MMP-2 and that it affected cell growth and tumor size and weight both in vitro and in vivo." (PMID 26202311, 2015). "In contrast, IL-12 production could significantly be enhanced by treatment of DC-tumor hybrids with inhibitors of the PI3K and mTOR." (PMID 26605345, 2015). "Moreover, the dual PI3K/mTOR inhibitor, NVP-BEZ235 inhibits Akt phosphorylation, reduces ACC cell proliferation in vitro, and reduces tumor size in xenograft mice." (PMID 26793165, 2015).
tumor (continued). "Rapamycin, an inhibitor of mTOR, can abrogate RMS tumor growth in a xenograft mouse model." (PMID 26420980, 2015). "Again, MEK but not mTOR inhibition results in consistently altered tumor vascularity and angiogenic cytokine/chemokine expression in MOC tumors." (PMID 26506415, 2015). "Finally, NVP-BEZ235 (PI3K/mTOR inhibitor) treatment in combination with docetaxel was more effective than chemotherapy alone at decreasing the human PCSC population and preventing tumor formation in vivo." (PMID 25595909, 2015). "Because EGFR/PI3K/Akt/mTOR signaling promotes tumor cell proliferation, we next examined the effect of PROG and TMZ on the cell proliferation marker PCNA, which is often used for grading different neoplasms." (PMID 26110872, 2015). "Our finding that mTOR inhibition leads to a CD8 cell dependent anti-tumor response in RAS-mutant, immunogenic MOC1 tumors is novel and suggests that mTOR targeting therapies may be useful in multiple tumor types regardless of underlying driver mutations." (PMID 26506415, 2015). "Interestingly, PML is also reported to contribute to GBM resistance to mTOR targeted therapies, suggesting its involvement in GBM tumor progression." (PMID 26510911, 2015). "Molecular analysis suggested that the tumor suppression effects of gal-1 silencing might be due to downregulation of COX-2/PGE2 and AKT/mTOR pathways." (PMID 25605013, 2015). "Grb10 has not previously been shown to be intrinsically oncogenic either in vivo or in vitro, nor have tumor-promoting functions of mTOR, the best understood phosphorylator of Grb10, been shown to be Grb10-dependent." (PMID 26000738, 2015). "In conclusion, this study provides preclinical proof-of-concept that the combination of a PI3K/mTOR inhibitor with an AR inhibitor results in a synergistic anti-tumor response in non-CRPC and CRPC models." (PMID 26506516, 2015). "Immunoblot analysis of tumor lysates revealed that the combination of fisetin and sorafenib further reduced expression of PI3K, enhanced PTEN expression, and decreased phosphorylation of AKT and mTOR as compared to monotherapy." (PMID 26299806, 2015). "Also, combined targeting of the mTOR pathway and the mitotic checkpoint protein aurora kinase A, using rapamycin + MLN8237, synergistically reduced uLMS cell growth in vitro, as well as tumor growth in an in vivo model." (PMID 26576131, 2015). "Interestingly, the addition of an mTOR inhibitor to BH3 mimetics reduces the expression of the antiapoptotic protein Mcl-1 and allows high BIM levels to “prime” tumour cells for apoptosis." (PMID 26639561, 2015). "In summary, the results from this study provided novel evidences that metformin could inhibit cell proliferation and tumor growth through targeting multiple key genes involved tumor proliferation, growth and metastasis, notably PTEN/Akt/mTOR pathway." (PMID 25909163, 2015). "PTEN links PI3K, Akt, mTOR, and ERK pathways together to induce tumor cell apoptosis." (PMID 26042820, 2015). "Although metformin has been shown to activate AMPK, which subsequently inhibits mTOR activity by phosphorylating and stabilizing the tuberous sclerosis complex-2 (TCS2) tumor suppressor, it has also been suggested that metformin can directly inhibit mTOR signaling independently of AMPK activation." (PMID 24887156, 2014). "Moreover, activation of Akt/mTOR pathway appears to stimulate accumulation and decrease degradation of HIF-1α in hypoxic tumor cells." (PMID 25140303, 2014). "High VEGF levels promote the production of abnormal vessels and binding of VEGF to its corresponding receptor leads to the activation of the PI3K/Akt/mTOR and Ras/Raf/MAPK pathways that in turn promote not only angiogenesis but also proliferation, differentiation and survival of tumor cells." (PMID 24717239, 2014). "The absence of tumor responses with mTOR inhibitors also indicates a lack of activity of mTOR inhibitors for FBXW7 positive patients." (PMID 24586741, 2014).
tumor (continued). "Importantly, the dual PI3K/mTOR inhibitor, BEZ235, has displayed robust anti-PRKDC activities and inhibition of tumor growth in pre-clinical mouse models; CC-115 also has a similar mTOR/PRKDC dual inhibition activity." (PMID 25495526, 2014). "As our previous studies implicated sustained activation of the p38 signaling pathway in mTOR inhibitor resistance, we further tested whether alterations in DUSP10 activity would affect PP242 GBM tumor cell responses." (PMID 25568665, 2014). "As the significant changes of Akt, mTOR, and BAD along with the progression of tumor grades I to III, it may correlate with the increasing number of lipid rafts." (PMID 25243186, 2014). "The sensitivity of xenografts with or without mTOR siRNA to cisplatin was evaluated in the transplantable tumor of ESCC." (PMID 24818169, 2014). "Especially, miR-149 may function as a tumor suppressive miRNA and play an important role in inhibiting the HCC tumorigenesis by modulating the AKT/mTOR pathway." (PMID 25424347, 2014). "We discovered that simultaneous inhibition of mTOR and metabolism with AZD8055 plus 2-DG combination was significantly more effective at inhibiting tumorigenesis and preventing sustained tumor growth that would occur through the activation of MAPK survival pathways." (PMID 25436981, 2014). "In the group of low blood vessel density count, 65% (26/40) of the cases did not express p-mTOR neither in the tumour nor non-tumour sections (P=0.003, data not shown)." (PMID 25202348, 2014). "In this study, the expression level of mTOR was examined by immunohistochemistry in human ESCC specimens, and the effects of mTOR siRNA and cisplatin alone or combined on cell proliferation, tumor growth, and cell apoptosis were, respectively, investigated in EC9706 cells and xenografts." (PMID 24818169, 2014). "Since VEGF is upregulated as a consequence of Akt–mTOR–HIF-1α signaling, any strategy that inhibits this pathway can be hypothesized to lower VEGF expression and tumor progression." (PMID 24436017, 2014). "In GBM, the mTOR kinase inhibitors CC214-1 and CC214-2 inhibit rapamycin-resistant mTORC1 and mTORC2 signaling, thus blocking protein translation, cell proliferation, and tumor growth." (PMID 25610711, 2014). "Of note, mTOR inhibitor temsirolimus has also demonstrated evidence of HIF-1α inhibition, and a clinical trial combining temsirolimus with bevacizumab and liposomal doxorubicin demonstrated extensive anti-tumor activity in multiple tumor types." (PMID 25373733, 2014). "Specifically, tumor suppressor genes that negatively regulate mTOR, such as PTEN, AMPK, LKB1, and TSC1/2 stimulate autophagy while, conversely, oncogenes that activate mTOR, such as class I PI3K, Ras, Rheb, and AKT, inhibit autophagy, suggesting that autophagy is a tumor suppressor mechanism." (PMID 25328887, 2014). "The PI3K/AKT/mTOR signaling pathway is downstream of insulin/IGF-1 signaling and modulates cell survival, proliferation, and metabolism under physiological and pathological conditions, including PCOS and tumor development." (PMID 24887156, 2014). "Temsirolimus (CCI-779) is another intravenous mTOR inhibitor and a prodrug of rapamycin, that binds to the intracellular protein FKBP-12 and leads to cell cycle arrest in G1 phase; it also inhibits tumour angiogenesis by reducing the synthesis of vascular endothelial growth factor (VEGF)." (PMID 25215588, 2014). "The ERα gene signature was used to filter expression levels in tumor samples (either ERα-positive or ERα-negative) and the mTOR associated genes Rictor, Raptor, Rheb, TSC1, TSC2, and mTOR were analyzed." (PMID 25283550, 2014). "The mTOR inhibitor rapamycin (sirolimus) inhibited PEL cell growth in a murine xenograft model, but mTOR inhibition with rapamycin paradoxically induces expression of the serine/threonine kinase Akt and tumor cell growth, resulting in treatment failures." (PMID 24587336, 2014).
tumor (continued). "GDC-0980 alone or in combination with CDX reduced tumor growth more than GDC-0941, suggesting that concomitant targeting of mTOR provides additional therapeutic benefit or alternatively that the pharmacodynamics of the dosing protocol was superior for GDC-0980." (PMID 25103565, 2014). "Accordingly, it is also a possibility that activation of the mTOR pathway might take place in NPC cells after BALF3 expression, in addition to low-dose DNA damage, which lead to tumor progression." (PMID 25261366, 2014). "The mammalian target of rapamycin (mTOR) inhibitor, sirolimus inhibits PEL cell growth in a murine xenograft model, but which paradoxically induces expression of the serine/threonine kinase Akt and tumor cell growth, resulting in treatment failures." (PMID 24708874, 2014). "The positive rate of mTOR expression was found to be much higher in tumor cells, whereas little or no expression in normal gastric tissues was observed." (PMID 25003395, 2014). "However, the unique biological features that define bladder tumourigenesis and tumour progression, together with the intrinsic complexity of the PI3K/Akt/mTOR pathway, are likely the predominant factors in this disease." (PMID 25202348, 2014). "Pre-clinical longitudinal studies that targeted the PI3K and p70S6K pathways with competitive NVP-BEZ235 inhibitor was not as effective at reducing tumor volume and burden as targeting mTOR with AZD8055 or glycolysis with 2-DG mono-therapies." (PMID 25436981, 2014). "This is in contrast to absent staining of S6K and 4E-BP1 in MTOR wild-type tumor regions in a ccRCC previously reported." (PMID 25159823, 2014). "Additionally, immunohistochemical analysis of the mTOR substrates S6K and 4E-BP1 in all tumor regions revealed enhanced staining of either or both substrates relative to normal kidney in a pattern consistent with the proteomic data." (PMID 25159823, 2014). "Where there is activity observed with allosteric mTOR inhibitors, they appear to be cytostatic, primarily stabilizing clinical disease, rather than resulting in tumor regression." (PMID 25261369, 2014). "The present study used immunohistochemistry to evaluate UBC sections containing tumour and non-tumour areas from 76 patients, for the detection of p-mTOR, CD31 and D2-40 (blood and lymphatic vessels identification, respectively)." (PMID 25202348, 2014). "In this study, although vertical blockade produced sustained suppression of signaling activities in the IGFR/PI3K/Akt/mTOR pathway of all the HCC cells tested, the impact on survivin expression and subsequent anti-tumor synergy varied among different combinations and cell lines." (PMID 24387108, 2014). "In tumor tissues from a mouse xenograft model established with human MM cell line JJN3, both AKT and mTOR activation was also decreased by C96, which is consistent with studies at the the cellular level, therefore, C96-delayed myeloma tumor growth is consistent with its inhibition on PI3K." (PMID 25003534, 2014). "The mTOR inhibitor temsirolimus was tried in combination with the anti-VEGF antibody bezacizumab in a clinical case series focusing on patients with neurofibromatosis 2; of the two patients on this regimen, one achieved a 33% reduction in tumor size." (PMID 24393766, 2014). "In our study, mTOR inhibitors showed a cytostatic effect on tumor growth (growth inhibition) but did not reduce original tumor volume over time." (PMID 24708766, 2014). "Another possibility is that the mTOR pathway is not the major target of metformin and anti-tumor activity is exerted independent of the pathway." (PMID 23922888, 2013). "Taken together, our results indicate that the combination of Rapamycin/Cl-1040/17-AAG decreases tumor metastasis, most likely via the transcriptional suppression of Slug, which is concomitantly expressed by the activation of the MAPK/ERK, PI3K/Akt/mTOR, and Hsp90/AR." (PMID 24130883, 2013).
tumor (continued). "AMPK directly phosphorylates TSC2 and raptor to suppress signaling through mTOR pathway, and mTOR pathway hyperactivity in the LKB1-deficient state is believed to account for some, but not all of LKB1 tumor suppressor functions." (PMID 24086281, 2013). "Rapamycin, the naturally occurring inhibitor of mTOR, and several recently developed rapamycin analogs (RAD001, CCI-779, AP23576, AZD8055) inhibit the growth of cell lines that have been derived from many tumor types in vitro and tumor models in vivo." (PMID 23537100, 2013). "Mammalian target of rapamycin (mTOR) is a key kinase acting downstream of the activation of PI3K, and mTOR that acts as a master switch of cellular catabolism and anabolism determining tumour cell growth and proliferation." (PMID 23905676, 2013). "Indeed, we show here that the most durable tumor responses and the highest levels of apoptosis were observed in mice treated with the FGFR inhibitor in combination with either the PI3K/mTOR inhibitor or the pan ErbB inhibitor." (PMID 23343422, 2013). "The tumor suppressive role of klotho may be initiated by downregulation of IGF-1 receptor phosphorylation, and subsequent decreases in IRS-1, PI3K, Akt, and mTOR phosphorylation." (PMID 23432957, 2013). "The mTOR inhibitor rapamycin (sirolimus) was approved by the FDA in 1999 to prevent renal transplant rejection and is a clinically approved immunosuppressive agent with promising anti-tumor properties." (PMID 23815869, 2013). "We provide evidences that in hypoxia conditions metformin was not able to activate AMPK and inhibit mTOR signaling, which likely prevents the inhibitory effects of metformin on tumor growth." (PMID 24391834, 2013). "Consistently with the inhibition of mTOR we measured increased accumulation of LC3B, a widely used autophagic readout, and this increased LC3B-mediated autophagy may contribute to tumor growth." (PMID 23922894, 2013). "As areas of the tumor become hypoxic, a hypoxia inducible factor (HIF) survival response may be initiated but soon aborted due to mTOR inhibition preventing HIF translation and downstream VEGF transcription." (PMID 23533410, 2013). "Thus the higher levels or activity of eIF4E often found in tumour cells may not only enhance the synthesis of growth-promoting or anti-apoptotic proteins (translated from relatively “weak” mRNAs) but also desensitize the cells to physiological stresses and the inhibition of mTOR." (PMID 23940704, 2013). "The requirement for SCD in tumor initiation and progression as well as the role of SCD in mediation AKT/mTOR induced tumor cell proliferation have not been tested using genetic models, such as SCD1 null mice, to date." (PMID 24069385, 2013). "Among the molecular pathways altered in tumor cells harboring KSHV, or following KSHV de-novo infection is phosphatidylinositol-3-kinase (PI3K)/AKT/mammalian target of rapamycin (mTOR), which is an ubiquitous pathway that controls cell survival and cell metabolism." (PMID 24422998, 2013). "Moreover, daily treatment of metformin led to a substantial inhibition of tumor growth in a xenograft model with concomitant decrease in the expression of proliferating cell nuclear antigen (PCNA), cyclin D1 and p-mTOR." (PMID 24351837, 2013). "In a series of 30 primary NB tumor samples, phospho-Akt and mTOR was detected in all samples, but was not seen in the Schwannian stroma and non-malignant adrenal medulla." (PMID 23638435, 2013). "As PI3K and mTOR are also downstream of VEGFR2, the principal VEGF receptor signaling in endothelial cells, mTOR has a potential dual neovascularization function in both tumor and endothelial cells." (PMID 23516584, 2013). "The fact that three of these four effector pathways have key proteins (namely, Raf, mTOR, PKC- ζ) that are PA-dependent may suggest how LPAAT-β knockdown could be this effective at inhibiting tumor cell growth." (PMID 24205284, 2013).